RASSF5 (Ras association domain family member 5)
Diseases named in the same sentence as RASSF5 in open-access papers (continued):
Sharing a sentence is not in itself a finding about the gene and the disease.
tumor (47 papers, 2004 to 2025). "RASSF5 belongs to the ras-association domain family, which is generally known as a tumor suppressor." (PMID 34681900, 2021). "If any deleterious mutation happens to occur in this RA domain, the overall tumor suppressive activity of RASSF5 will be significantly reduced." (PMID 32884013, 2020). "Ras association domain-containing protein 5 (RASSF5), one of the prospective biomarkers for tumors, generally plays a crucial role as a tumor suppressor." (PMID 32884013, 2020). "Ras association domain-containing protein 5 (RASSF5) is the leading member of Ras effector super family protein that prevents tumor growth by facilitating G1/S arrest of cell cycle." (PMID 32884013, 2020). "Proteins from the Ras association family (Rassf, especially Rassf1 and Rassf5) are tumor suppressors that are activated by Ras-GTP, triggering apoptosis via e.g., activation of mammalian sterile 20-like (MST1) kinase." (PMID 24216995, 2013). "The native tumor suppressor function of RASSF5 could explain the increase in senescence of A549 cells upon transfection with RASSF5 variants." (PMID 34717958, 2021). "Three of the RAS-association domain family members (RASSF2, RASSF3, and RASSF5) were involved in the network analysis using all methylomics decision tree models, which are known as tumor suppressor genes and epigenetically inactivated in different tumor types." (PMID 31552087, 2019). "RASSF5 is a member of the Ras association domain and serves as tumor suppressor." (PMID 30286143, 2018). "Loss of RASSF5, the only direct effector of H/K/NRAS, cooperates with activated KRAS oncoproteins to drive cellular transformation and tumor growth." (PMID 39009833, 2024). "Protein–protein interaction analysis revealed a strong association of ANGPTL proteins with several tumor-suppressor proteins such as ITGB3, ITGAV, and RASSF5." (PMID 37375208, 2023). "Overall, we found that NPM3 was positively associated with genes that promote tumor proliferation, with NPM3 positively regulating the expression of CCNA2 and MAD2L1, and NPM3 was negatively correlated with the tumor suppressor RASSF5." (PMID 37254219, 2023). "Wild-type AIP4 induces tumor poly-ubiquitination and degradation of suppressor protein RASSF5 to suppress RASSF5A-mediated G1 arrest and apoptosis in HEK293T cells." (PMID 35177982, 2021). "RASSF2 and RASSF5 belong to the RASSF family that shares a region of homology (the Ras association domain), and RASSF proteins functions as tumor suppressors by interacting either directly or indirectly with activated Ras and regulating cell growth signaling." (PMID 34604090, 2021). "We demonstrate that Rassf5 suppresses progenitor cell renewal to limit oncogenic growth, which suggests a mechanism of Rassf5-mediated tumor suppression via differentiation." (PMID 33393458, 2021). "Using a combination of computational design and in vitro evolution, we engineered high-affinity Ras-binding proteins starting from a natural Ras effector, RASSF5 (NORE1A), which is encoded by a tumor suppressor gene." (PMID 34717958, 2021). "Rassf5 has been long considered a tumor suppressor in epithelial cancers, where it is often silenced through methylation and was shown to promote both apoptosis and senescence." (PMID 33393458, 2021). "After the combined treatment, it was found that two EZH2 target genes were upregulated, namely the tumor suppressor gene RASSF5 (ras association domain family member 5) and ITGB2 (integrin subunit Beta 2), which is associated with anti-tumor immunity." (PMID 32751889, 2020). "In various tumor tissues, low RASSF5 expression has been discovered and can therefore be considered as a prospective biomarker for tumors." (PMID 32884013, 2020). "One of the major targets of TET1 is RASSF5, a tumor suppressor—as TET1 overexpression upregulates RASSF5 expression by inhibiting the hypermethylation of the RASSF5 promoter." (PMID 31426393, 2019).
tumor (continued). "Here, we review autoinhibition and release mechanisms at the membrane focusing on three representative Ras effectors, Raf protein kinase, PI3Kα lipid kinase, and NORE1A (RASSF5) tumor suppressor, and point to the ramifications to drug discovery." (PMID 30269291, 2018). "Rassf1A−/− mice are viable, potentially due to compensation from the close homologue Rassf5 (49% identity) which has similar effects in the early embryo, but tumour prone." (PMID 29382819, 2018). "RASSF5/NORE1 is an important tumor suppressor, which can inhibit tumor growth by promoting G1/S arrest." (PMID 29156803, 2017). "Instead, SAV1 SARAH and MST2 SARAH form a heterodimer, similar to that formed by the SARAH domains of MST2 and one of the RASSF family of tumor suppressors, RASSF5." (PMID 29063833, 2017). "RASSF1A and RASSF5 are key bona fide tumor suppressor genes, whose protein products have been shown to regulate MST1/2 kinase activity." (PMID 27716844, 2016). "RASSF5 has been identified as a tumour suppressor in several studies focusing on cancers in humans." (PMID 41164230, 2025). "Interestingly, the RA of the tumor suppressor RASSF5 interacted only with growth-promoting RAS GTPases." (PMID 39009833, 2024). "An example involves mutations in the histone methyltransferase EZH2, whose activity causes reduced expression of RAS association domain-containing protein 5 (RASSF5) and integrin beta chain-2 (ITGB2); these are proteins that are involved in anti-tumor response." (PMID 38672652, 2024). "Our research further proved that RASSF5 acted as a tumor suppressor gene." (PMID 36354693, 2022). "Overall, RASSF5 may exert tumor-suppressive functions through multiple context-dependent mechanisms." (PMID 34681900, 2021). "We hypothesized that enhancing Ras-binding affinity of RASSF5 could further enhance its tumor suppressor properties by prolonging the half-life of the Ras-RASSF5 complex." (PMID 34717958, 2021). "Additionally, we observed a significant increase in RASSF5 levels in TET1-overexpressing tumor tissue samples." (PMID 29156803, 2017). "NORE1A (RASSF5) is a member of the RASSF family of Ras effector/tumor suppressors." (PMID 27023610, 2016). "The evidence we have so far indicates that the RASSF family members RASSF1A and RASSF5 (also known as NORE1 or RALP) are tumor suppressors that mediate apoptosis through different effectors including MST1/2 kinases, but their exact regulation by RASSF proteins is incompletely understood." (PMID 27716844, 2016). "Our findings indicate that ANGPTL3 and ANGPTL8 play a pivotal role in cancer progression by interacting with tumor-suppressor proteins such as ITGB3, ITGAV, RASSF5, and FNDC5." (PMID 37375208, 2023). "GATA3, FOXA1, RASSF5, PTPN6, and TRNP1, involved in the luminal markers and negative regulation of cell proliferation, are related to tumor suppression and chemotherapy resistance." (PMID 36344487, 2022). "The other cluster including RASSF5, RASSF6, STAT1, CEACAM1, BNIP3L and SOCS2 is related to tumor suppression." (PMID 32201535, 2020). "To demonstrate that the observed decrease in the tumor cell proliferation rate was due to the TET1-dependent activation of RASSF5, we performed RASSF5 knockdown experiments." (PMID 29156803, 2017). "In common with other cancers, WTs also show tumour suppressor gene silencing which includes genes such as HACE1 (73% of tumours analysed), RASSF1 (56%), CASP8 (43%), MGMT (30%), RASSF5/NORE1 (15%), and CDKN2A (10–15%)." (PMID 19956686, 2009). "Members of the RASSF family (such as RASSF1A and RASSF5/NORE1A) also play important tumor suppressive roles in the non-classical Hippo pathway." (PMID 40486910, 2025).
tumor (continued). "RAS bound with RASSF5, activate MST1/235,44 to form STK3/MST2 and STK4/MST1 complexes in the hippo signaling pathway that plays a crucial role in tumor suppression by limiting proliferation and stimulating apoptosis where SAV1, MOB1A/B act as effector molecules." (PMID 32884013, 2020). "In addition, 5-fluorouracil (5-FU), LIN28A, let-7, RASSF5, and ALKBH5 were shown as top 5 upstream regulators, all of which have been reported to be related to tumor formation." (PMID 30286143, 2018). "In the case of RASSF5 tumor suppressor, pharmacological efforts should not be aimed at promoting the autoinhibition but abolishing it." (PMID 30269291, 2018). "For example, RASSF5 methylation highly correlated to MYCN amplification and INRG stage M. Furthermore, high methylation of RASSF6 was correlated to unfavorable outcome, 1p deletion and MYCN amplification in our tumor material." (PMID 22695170, 2012). "The results suggested that, the high expression of C1orf74, HK2, SLC22A3, SNX10 and URB2 and Neutrophils, as well as the low expression of RASSF5 and CD8+ T cells was related to the poor prognosis of CC patients, which might serve as the key prognostic biomarkers of tumor." (PMID 36354693, 2022). "These genes that were only identified by one platform included well known tumor suppressors such as CDKN2A and RASSF5 that obviously warrant investigation, but did not meet the criteria for this specific study." (PMID 24454902, 2014).
cancer (33 papers, 2006 to 2025). A tumor composed of atypical neoplastic, often pleomorphic cells that invade other tissues. "We analyzed mutational signatures in aging Rassf5−/− and wildtype littermate control mice using the Catalogue of Somatic Mutations in Cancer (COSMIC) database." (PMID 37247756, 2023). "In conclusion, engineered RASSF5 variants provide an attractive therapeutic strategy able to oppose cancer development by means of inhibiting of procancer pathways and stimulating anticancer processes." (PMID 34717958, 2021). "We next set out to test the activity of the engineered RASSF5 variants in cancer cells." (PMID 34717958, 2021). "Like other RA domain family (RASSF) members, Rassf5 lacks enzymatic activity and is often epigenetically silenced in cancer." (PMID 33393458, 2021). "RASSF5 belongs to a large family of cancer suppressor effectors that are inactivated by promoter hypermethylation in numerous cancer cell lines and primary cancers." (PMID 34717958, 2021). "The natural role of RASSF5 as a cancer suppressor that induces senescence and proapoptotic pathways makes it an attractive candidate for inhibiting Ras-driven cancers." (PMID 34717958, 2021). "Stenotrophomonas, an opportunistic pathogen with increased colonization/infection in cancer patients, exhibited extensive positive associations with the hypermethylation of genes, including multiple TSGs in CRC, such as ESR1, RASSF5, DIRAS1, CADM1, ST5, GJB2, FAM172A, and HIVEP3." (PMID 38840170, 2024). "Thus, we have turned to transient transfection and transfected 12 engineered constructs and two WT RASSF5 into A549 cells and measured their effects on various cancer-related pathways." (PMID 34717958, 2021). "Our results further revealed that upregulating MAPK8IP1P2 activated Hippo signaling by disrupting the repressive effect of miR-146b-3p on NF2, RASSF1, and RASSF5 expression by sponging miR-146b-3p as ceRNA, which further suppressed anoikis resistance in thryoid cancer cells." (PMID 33489905, 2020). "Knockdown of Gls1 increased the expression of Cdkn1a and Cdkn1b and decreased the expression of some critical oncogenes for cancer cell survival, such as c-Myc, Cdk4, and NfκB, as well as some genes which are essential for MM cell survival, such as Irf4, Prdm1, Csnk1α1, and Rassf5." (PMID 31666930, 2019). "CYP24, FOSB, PCDH10, THBS2, and RASSF5 were selected as representative genes for further analysis, as they are well-known regulators of cancer cell proliferation and apoptosis, and the results obtained by qPCR analysis were shown to support our previously obtained results." (PMID 29156803, 2017). "However, RASSF5 is frequently silenced in human cancers through promoter methylation, and the induction of RASSF5 expression was shown to inhibit cancer cell growth in humans." (PMID 29156803, 2017). "ITCH involved in cancer progression mainly depends on its ability to regulate protein stability and the target proteins including p63, p73, Notch1, Dvl2, RASSF5, and LATS1." (PMID 27642589, 2016). "KEGG pathway analysis further highlighted the role of S6K1 in cancer progression, in which the depletion of S6K1 could re-express a group of tumor suppressor genes including RASSF5, RASSF6, STAT1, CEACAM1, BNIP3L and SOCS2." (PMID 32201535, 2020). "NORE1A (RASSF5), the other major RASSF family member, is also frequently inactivated in human cancers and serves as a Ras effector connecting Ras to the Hippo pathway, is a key mediator of Ras-induced senescence, and links Ras to the control of protein stability." (PMID 26999212, 2016). "RASSF5, also called NORE1 (Novel Ras Effector 1), is localized at 1q32.1 and has a 60% similarity to RASSF1A, the most commonly described methylated gene in cancer so far." (PMID 22695170, 2012).
cancer (continued). "Since RASSF5 and other RASSF family members are inactivated by promoter hypermethylation in numerous cancer cell lines and primary cancers, reintroduction of small proteins derived from such effectors with enhanced Ras affinity is an attractive strategy against cancer." (PMID 34717958, 2021). "RASSF5 (RAS association domain family member 5): The combination of RASSF5 along with four other DNA methylation markers can effectively differentiate between benign prostate biopsy cores from non-cancer patients and cancer cores, and can be used to identify patients at risk without repeat biopsies." (PMID 34290571, 2019).
RASSF5 also shares sentences with these, for which no sentence is quoted: hepatocellular carcinoma (3 papers); infection (3); colorectal tumor (2); gastric cancer (2); Wilms tumor (2); Alzheimer disease (1); autoimmune disease (1); breast tumor (1); Cirrhosis (1); colorectal (1); dengue (1); follicular thyroid carcinomas (1); glioma (1); hepatocellular adenoma (1); large cell carcinoma (1); leukemia (1); neuroblastic tumor (1); Obesity (1); osteonecrosis (1); rhabdomyosarcoma (1); Splenomegaly (1); type 2 diabetes (1).